TEX26 (testis expressed 26)
Synonyms: C13orf26; MGC40178
Tractability: No criterion of Open Targets' tractability assessment is met for any kind of drug.
Gene: Protein-coding gene on chromosome 13 (30,932,656 to 30,975,500, forward strand). Ensembl gene ENSG00000175664.
Subcellular location (Human Protein Atlas): Golgi apparatus
Gene Ontology:
Cellular component: cytoplasm
Genetic constraint (gnomAD): Loss-of-function variants: 30 observed, 33.01 expected, observed/expected ratio (o/e) 0.91, 90% interval 0.68 to 1.23. The upper end of that interval is the gene's LOEUF score, 1.23, which puts it in group 5 of 6, group 1 being the genes least tolerant of losing a copy. Missense variants: 346 observed, 315.79 expected, observed/expected ratio (o/e) 1.1, 90% interval 1 to 1.2. Synonymous variants: 129 observed, 111.29 expected, observed/expected ratio (o/e) 1.16, 90% interval 1 to 1.34.
Homologues: Orthologues: chimpanzee TEX26 (98% identical), macaque TEX26 (93% identical), rabbit TEX26 (73% identical), dog TEX26 (73% identical), pig TEX26 (67% identical), mouse Tex26 (59% identical), rat Tex26 (58% identical), tropical clawed frog tex26 (32% identical).
Diseases named in the same sentence as TEX26 in open-access papers:
TEX26 is named in the same sentence as 2 diseases in open-access papers, as found by Europe PMC text mining. Sharing a sentence is not in itself a finding about the gene and the disease. The quoted sentences say what the papers report.
Bicuspid aortic valve (1 paper, 2019). The presence of an aortic valve with two instead of the normal three cusps (flaps). "Analyses completed by sex discovered dissimilar variants related to bicuspid aortic valve (BAV) in men (EGFR rs533525993 and TEX26 rs12857479) and females (NKX2‐5 rs2277923)." (PMID 30834692, 2019).
TEX26 also shares sentences with these, for which no sentence is quoted: glioma (1 paper).